CCNE1 (cyclin E1)
Diseases named in the same sentence as CCNE1 in open-access papers (continued):
Sharing a sentence is not in itself a finding about the gene and the disease.
tumor (continued). "miR-154-5p acts as tumor suppressor in osteosarcoma and its upregulation inhibits the proliferation, migration and invasion in vitro as well as in-vivo tumor growth via the dysregulation in the pro-apoptotic proteins’ expression and the cell cycle regulators such as E2F5, Cyclin E1 and CDK2." (PMID 35755302, 2022). "Additionally, IHC staining showed decreased expression of Ki-67, cyclin D1, cyclin E1, and E2F1 in sh-CENPU-treated Huh-7 xenograft tumours." (PMID 35844791, 2022). "CCNA2, CCNB1, and CCNE1 were co-expressed with BIRC5, a well-known cancer therapeutic target which directly regulates both apoptosis and mitosis in cancer cells during tumorigenesis and tumor metastasis." (PMID 33996604, 2021). "This gain can be explained by the platinum resistance in CCNE1-overexpressing tumours and not the direct interaction between antiangiogenic therapy and CCNE1 overexpression." (PMID 34567247, 2021). "Ccne1−/− tumours revealed diminished levels of Ccr2 and Ccr5, which further indicates the decrease in infiltrating myeloid subpopulations in absence of CCNE1." (PMID 34830835, 2021). "In consensus with these findings, CD45-positive leukocytes and TAM1 negatively correlated with tumour size in the Ccne1-depleted cohort, which was not the case in control or Cdk2−/− animals." (PMID 34830835, 2021). "Notably, tumor sample analysis showed that RB1 protein abundance was slightly increased, while protein levels of CDK6, cyclin D3, cyclin E1, cyclin D1, SKP2, and CDK2 were significantly decreased in the combination treatment group." (PMID 34508104, 2021). "Additionally, it was found that BMMSC-derived exosomal miR-144 suppressed growth of tumor cells and colony formation in NSCLC by targeting CCNE1 and CCNE2." (PMID 33658392, 2021). "CCNE1 expression was upregulated in tumour samples of two of the three major HCC subtypes, characterised by a common signature of high proliferation, low differentiation, high tumour grade, vascular invasion, chromosomal instability and immune infiltration." (PMID 34830835, 2021). "In addition, CCNE1, CCNE2, CCNB2, CCNA2, and CDK1 genes were highly expressed in fetal tumor tissues." (PMID 34395530, 2021). "In this study, the differential expression analysis showed that among all cyclin family members, there were six significant DEGs (CCNA2, CCNB1, CCND1, CCNE1, CCNF, and CCNJL), five of which were overexpressed in tumor samples compared to normal controls, while CCNJL was downregulated." (PMID 33996604, 2021). "Moreover, we detected 15 gene amplifications in six different tumor specimens, including AR, CCND1 (n = 2), FGF19 (n = 2), FGF3 (n =2), KRAS (n = 2), MYC (n = 2), CCND3, CCNE1, CDK6, and RICTOR." (PMID 33203166, 2020). "Her tumor showed the similar BRCA1 5370C>T (R1751X) alteration but notably also showed a CCNE1 copy number of 7 by WES." (PMID 32709856, 2020). "For example in tumor P22 (basal), three focal amplicons encompassing the VEGFA, MYC and CCNE1 loci were found in varying proportions and in certain instances (VEGFA and CCNE1) in a mutually exclusive manner in sequenced single-nuclei (p-value=0.003 – Fisher’s Exact Test)." (PMID 32401198, 2020). "Recent findings showed that METTL3 expression was higher in CRC tissues than in normal tissues and that this feature indicated poor prognosis; upregulation of METTL3 promoted CRC tumor growth by stabilizing SRY-box 2 (SOX2) and cyclin E1 (CCNE1) mRNA in an m6A-dependent manner." (PMID 32429972, 2020). "In the primary tumor, most CNV were found in MYC, CCND1, ERBB2 and CCNE1." (PMID 33298978, 2020). "An interesting observation is that CCNE1 overexpression never occurred in all tumour cell nuclei in tumour tissue." (PMID 32391646, 2020). "Matched pre- and post-neoadjuvant chemotherapy tumor samples with and without cyclin E1 overexpression were correlated with the degree of pathological response to treatment using chemo-response scores." (PMID 32380689, 2020).
tumor (continued). "Indeed, we also observed correlations between mRNA expression of CCNE1 or CDC25A and copy number load in various tumor types." (PMID 33028815, 2020). "Among the tumor-related genes, the top amplified genes included ERBB2 (17q21), MYC (8q24), GNAS (20q13), EGFR (7p11), ZNF217 (20q13), CCNE1(19q12), NCOA3 (20q13), and CDK6 (7q21), and the most frequently deleted genes were CDKN2A (9p21), CDKN2B (9p21), KIT (4q12), SMAD4 (18q21), and FGFR1 (8p12)." (PMID 31541076, 2019). "Regardless of the mechanism employed by these tumor cells that leads to an upregulated CCNE1/E2F signature, elacestrant retained anti-tumor activity in in vitro and in in vivo PDX models." (PMID 31852484, 2019). "Additionally, we observed a highly significant correlation between FOXM1 and CCNE1 mRNA and Cyclin E1 protein expressions in TCGA pan-cancer and HGSC primary tumor data." (PMID 30795624, 2019). "HER2/CCNE1-amplified PDCs were considerably resistant to an HER2 inhibitor, while combinational treatment consisting of an HER2 inhibitor with anti-WEE1 compound substantially suppressed tumor cellular growth." (PMID 31850215, 2019). "Tumor FR2048T displayed a translocation placing CCNE1 downstream the first untranslated exon of the highly expressed ERRFI1 gene, leading to a highly expressed ERRFI1-CCNE1 fusion." (PMID 30531861, 2018). "In conclusion, gga-miR-103-3p targets the CCNE1 and TFDP2 genes, and suppresses cell migration, which indicates that it might play an important role in MD tumor transformation." (PMID 26935418, 2016). "The present study demonstrates that physical interactions between ARID2 and the transcriptional factor E2F1 play pivotal roles in ARID2-mediated suppression of cyclin D1 and cyclin E1, supporting the notion that ARID2 acts as a tumor suppressor by targeting the Rb-E2F signaling pathway." (PMID 27351279, 2016). "The mRNA expression of some proliferation and invasion related genes such as CCND3, CCNE1, Ki-67 and MMP3 were all down-regulated in miR-15a/miR-16-1 overexpression group, elucidating the tumor-suppressive functions of miR-15a and miR-16-1 in gastric tumorigenesis." (PMID 25743273, 2015). "Meanwhile, among the target genes for miR-195 and miR-497 identified in the present study, top four target genes, CCNE1, CDC25A, CDK4 and CDK6, frequently upregulated in a tumor-specific manner only showed slight inverse correlation with these miRNAs in HCC tumors." (PMID 23544130, 2013). "We showed that pRb was heavily phosphorylated, hence inactivated, in many RB1-proficient TNBC tumor lines, and this correlated with high expression of Cyclin E1 in basal-A but not in basal-B tumors." (PMID 24265703, 2013). "Moreover, target genes frequently upregulated in HCC in a tumor-specific manner, such as CDK6, CCNE1, CDC25A and CDK4, showed an inverse correlation in the expression of miR-195 and miR-497, and their targets." (PMID 23544130, 2013). "In a re-analysis of those data, one prominentgene-expression feature included genes regulating the cell-cycle (e.g. CCNE1,CDK1, CDC25A), and involved in DNA replication(e.g. POLE2, MCM4, TK1) andchromosome dynamics (e.g. SMC4, CENPE), ostensiblyreflecting tumor cell proliferation levels." (PMID 21629784, 2011). "By contrast, in primary tumours high levels of CCNE1, but not CCNE2, predict a shorter relapse-free interval of tamoxifen-treated patients." (PMID 20180967, 2010). "One tumor had CDKN2A homozygous deletion and CCNE1 amplification." (PMID 18549475, 2008).
tumor (continued). "Notably, disrupting glucose uptake solely in Ccne1+ tumor cells did not replicate the increased T-cell trafficking observed with global GLUT1 inhibition." (PMID 38509063, 2024). "To further investigate this possibility, we performed a second experiment to enrich for the CAFs in the Ccne1+ immune-excluded model by FACS-sorting dsRED- CD45− CD31− CD90+ (non-tumor, non-immune, non-endothelial) cells and analyzing the purified CAFs by scRNA-seq." (PMID 38509063, 2024). "This confirms that prolonged CDK2 inhibition in vivo can exert sustained control of CCNE1-amplified tumors, and that rebound compensation by CDK4/6 is not present to a level sufficient to significantly restore Rb phosphorylation, cyclin A2 expression, or tumor growth." (PMID 38047585, 2024). "In vitro results showed that III-13 inhibited proliferation of a wide range of tumor cells, regardless of whether Cyclin E1 (CCNE1) was overexpressed or not." (PMID 38338471, 2024). "Thus, Ccne1 seems to be involved in the control of Il6 expression in the fibrotic and tumorous liver independent of Tnf." (PMID 37620309, 2023). "Association of CCNE1 expression with PFI remained significant in patients without residual tumor after surgery (R0, n = 19, p = 0.01), but exhibited a non-significant but similar trend in patients with residual tumor (R > 0, n = 72, p = 0.08)." (PMID 35169222, 2022). "Indeed, the Cyclin E1 gene is genomically amplified in many cancer types, including CRC, and its ensuing overexpression promotes cell cycle mis-regulation, CIN, cellular transformation, and tumor formation in mice." (PMID 36496990, 2022). "We could not measure CCNE1 expression in the remaining tumours due to the unavailability of tumour samples." (PMID 34567247, 2021). "Importantly, the deletion of Ccne1, but not of Cdk2, significantly reduced the number of Ki67-positive cells in tumours." (PMID 34830835, 2021). "The reason why we could not confirm the CCNE1 knockdown of tumor obtained from a xenograft mouse model is that it could be influenced by the in-vivo environment, via immune system-related T cells or NK cells." (PMID 34070839, 2021). "Alternatively, our findings in the HCC environment could be explained by an indirect, secondary effect due to reduced tumour load of Ccne1-depleted mice, independent of CCL2-driven chemotaxis or T cell-mediated activation via INFG." (PMID 34830835, 2021). "Moreover, patients with CCNE1 variation showed poorer survival prognosis compared to nonvariant tumor patients (p = 2.397e − 6)." (PMID 34734085, 2021). "Taken together, this study reports that replication stress induced by overexpression of Cyclin E1 and Cdc25A results in the formation of lagging chromosomes and chromatin bridges, which is further exacerbated by inhibition of ATR or WEE1 kinases, and results in exacerbated tumor cell killing." (PMID 33028815, 2020). "The specific function of OTUB1/Cyclin E1 axis in vivo could not be fully explained by subcutaneous tumor related experiments." (PMID 33537306, 2020). "To clarify the effects of cylcin E1 expression on HCC tumor progression, we studied the expression of cyclin E1 and inhibitory efficacy of regorafenib and sorafenib in HCC cells, and investigated a potential therapy that combines regorafenib treatment with cyclin E1 inhibition." (PMID 31349793, 2019). "Both tumor and adjacent tissues exihibited CCNE1 expression using the final staining score and only normal tissues did not have the expression of CCNE1." (PMID 31072916, 2019). "However, there were cases with high Cyclin E1 expression without 19q12 amplification and 19q12-amplified tumours with low Cyclin E1 expression." (PMID 27582547, 2017).
tumor (continued). "While Patients 5, 6, and 7 demonstrated a significant increase in nuclear YAP in tumor compared to non-neoplastic tissue, they only had a substantial increase in CCNE1 expression, with Cyr61 being downregulated in Patient 5 and unchanged in Patients 6 and 7, and CTGF unchanged in all three patients." (PMID 27605415, 2016). "CCNE1 staining was negative or low in all normal ovary and benign tumor tissues." (PMID 26204491, 2015). "In a disease setting, these results suggest that treatment failure in CCNE1 amplified tumors may relate to rapid repopulation of the tumor after chemotherapy and not cellular drug resistance specifically." (PMID 21103391, 2010). "Indeed, the absence of CCNE1 overexpression/amplification in a subpopulation of cells within a CCNE1-amplified bulk tumor could be an escape mechanism for therapies targeting this gene." (PMID 40738893, 2025). "Conversely, PC(16:0/18:1(9Z)), a metabolite significantly downregulated in ARMS, showed negative correlations with ARMS-unique proteins (cyclin-E1, r = −0.71; myotrophin, r = −0.68), which may reflect subtype-specific alterations in lipid metabolism related to tumor progression." (PMID 40710368, 2025). "However, whether there is a corresponding common pathway of CCNE1 in its translation, transcription, expression and other processes to produce effects in different tumor pathogenesis is still not clear." (PMID 39591374, 2024). "In this regard, we observed that glyCAF exhibit the strongest blocking of CD8+ T cell migration toward the tumor cells compared to the non-glyCAF, Ccne1+ cancer cells, and macrophages, Then, we investigated whether blocking GLUT1 in the glyCAF impacts their functions." (PMID 38509063, 2024). "Although this remains to be formally tested, a possible tumour suppressive role may arise through its relationship with SKP2, where EMI1 prevents the uncontrolled degradation of SKP2 by APC/CCDH1, thereby allowing SCFSKP2 to regulate Cyclin E1 abundance preventing its aberrant accumulation." (PMID 39358461, 2024). "More interestingly, Cyclin E1 could be mediated by G6PD overexpression and high Cyclin E1 expression predicted poor outcomes, which indicated that as a cell cycle-related molecular, Cyclin E1 might be a more crucial downstream target of G6PD in promoting ccRCC tumor proliferation." (PMID 34975298, 2022). "However, interventional deletion of Ccne1 resulted in significantly reduced tumour numbers and the cumulative tumour size of approximately 50% compared to controls, but had no impact on the mean or median tumour size." (PMID 34830835, 2021). "In addition, we found that tumor incidence in OTUB1 overexpressed group was significantly faster than that in the control group, while RO-3306 restrained the tumor incidence in the OTUB1 overexpression group, indicating the critical role of OTUB1/Cyclin E1 axis in tumor formation." (PMID 33537306, 2020). "Interestingly, cyclin E2 becomes expressed at high levels in immortalised mouse embryonic fibroblasts derived from E2F1 knockout animals, and is also expressed at high levels in chemically-induced tumours derived from the same mice, without concurrent changes to cyclin E1 expression." (PMID 20180967, 2010). "Although a pull-down assay confirmed that cyclin E1 binds with the first 441 amino acids of RSF1, full-length RSF1, but not the minimal binding domain of RSF1, has a tumour-promoting function." (PMID 34147108, 2021). "The results showed statistically significant differences in tumor volume between the control group and the AZD5438-treated group in CCNE1-amplified AFPGC PDX models, but not in non-CCNE1-amplified models." (PMID 34168152, 2021). "Of the four cyclins, CCNE1 and CCNE2 mRNA occurred at significantly higher levels in whole genome doubled (GD) tumours versus non-genome doubled (NGD) tumours in breast cancers." (PMID 32823571, 2020).
tumor (continued). "We then examined the relationship between gene amplification and genome doubling in breast cancer, by comparing CCNE1, CCNE2, CCND1 and CCND2 gene amplification in non-genome doubled and genome doubled tumours." (PMID 32823571, 2020). "Our main approach to identify cancer-related genes was to filter for the most frequent aberrations but we noted that well characterised cancer driver genes, such as CCNE1 and ERBB2, were not identified since they were amplified in less than 40% of tumours." (PMID 20386695, 2010). "Both CCNE1 (p < 0.001) and PLK1 (p < 0.001) showed higher expression in tumor tissue than in normal tissue, while the expression of SERPINA1 in both tumor and normal tissue was not significantly different (p = 0.541)." (PMID 36393842, 2022). "Our results implicate that the tumor microenvironment in this group is similar to non-BRCAmut HRD, however, the OS of this double classifier group is worse than OS in the non-BRCAmut HRD group and shows similarities to the group with CCNE1 amplification." (PMID 36497449, 2022). "RT-PCR analysis of the transcriptional expression of cell cycle genes showed a significantly increased expression of ccnA1, ccnB2, ccnD3, ccnE1, cdc25b, and E2F1 and a significantly decreased expression of ccnD2 in the Fhit-transfected versus non-transfected tumor cells." (PMID 32545680, 2020). "Indeed, recurrent integrations are most frequently found in the promoter region of human hTERT gene, but have also been observed in MLL4, CCNE1, and ALB genes, in tumour samples but not in the matched non-tumour samples." (PMID 30037029, 2018). "However, an independent prognostic value of Cyclin E1 overexpression was not confirmed by multivariate COX regression analysis adjusted for other parameters (patient age, tumour subtype and FIGO stage; p = 0.079)." (PMID 27582547, 2017). "Among them, the enrichment of HBV-DNA integration in TERT, CCNE1, and CCNA2 genes in tumoral samples has also been confirmed by analyzing the publicly available database VISDB, collecting 20558 HBV-DNA integration sites in tumor/peritumor/non-tumor liver samples from 45 publications." (PMID 36118192, 2022). "With the Wilcoxon rank test we find genes such as MYC, CCNE1, KRAS, NDRG1, MLL4 and MTSS1 for which data set specific normal tissue expression may not be significantly different from all tumor samples but is variable between low and high copy number tumor samples." (PMID 22174824, 2011).